CFL2 (cofilin 2)
Diseases named in the same sentence as CFL2 in open-access papers (continued):
Sharing a sentence is not in itself a finding about the gene and the disease.
tumor (11 papers, 2013 to 2025). "Taking the hubs individually, the results showed that expression of two DEGs, upregulated small nuclear ribonucleoprotein Sm D1 (SNRPD1) and downregulated cofilin 2 (CFL2), was associated with pathological T stage (size of the tumor and any spread of cancer into nearby tissue)." (PMID 38001634, 2023). "How CFL2 expression dynamics are involved in promoting tumor progression must be clarified by further studies." (PMID 38001634, 2023). "Our study suggests that regulation of CFL2 by hsa-miR-200b is a dynamic process during tumor progression and that this control plays essential roles in IGC development." (PMID 38001634, 2023). "Functional investigations revealed its overexpression displayed a positive role in the progression of tumor growth and metastasis via modulating miR-1299/CFL2 axis." (PMID 34307457, 2021). "This increase in CFL2 production likely assists the tumor in spreading both locally and metastatically at a much greater rate." (PMID 23497265, 2013). "The increase in CFL2 expression likely assists the higher-grade tumor cells in obtaining their migratory propensity by allowing for considerably higher F-actin turnover." (PMID 23497265, 2013). "The CFL2 expression can be seen to increase dramatically along with the grade of the tumor (p = 0.001)." (PMID 23497265, 2013). "However, our study suggests that regulation of CFL2 by hsa-miR-200b is a dynamic process during tumor progression and that this control plays essential roles in IGC development." (PMID 38001634, 2023). "Overall, the findings suggest that dynamic expression of CFL2 in IGC patients may be necessary for tumor progression and that this control may be performed by decreased expression of its repressor hsa-miR-200b." (PMID 38001634, 2023). "The authors also reported that CFL2 expression was correlated with tumor grade." (PMID 28362846, 2017). "CFL2 expression was also noted to increase significantly along with the grade of the tumor." (PMID 23497265, 2013). "We further observed an overall negative association between NME4 and tumor invasion markers like genes encoding matrix-degrading proteases (MMP7, ADAM17) and actin cytoskeleton remodelers (ROCK1, ROCK2, LIMK2, CFL2, MYO5A)." (PMID 34674701, 2021).
cancer (8 papers, 2017 to 2024). A tumor composed of atypical neoplastic, often pleomorphic cells that invade other tissues. "The cBioPortal analysis program identified 12 types of human cancer with significant CNAs in the chosen genes’ signature (CAP1, CAP2, CFL1, CFL2, DSTN)." (PMID 28423713, 2017).
myopathy (7 papers, 2010 to 2023). A disease of the muscle in which the muscle fibers do not function properly. "We then analyzed how the myopathy-causing Tpm3.12 variant changes the interactions of cofilin-2 with actin filament." (PMID 38003645, 2023). "To gain insight into the regulation of cofilin-2 activity by a myopathy-causing mutation in TPM3, we used the p.R91C substitution in Tpm3.12, which is associated with muscle weakness in patients and causes the hypocontractile phenotype in vitro." (PMID 38003645, 2023). "Mutations in CFL2 cause myopathies in humans, and its deletion is associated with lethality in mice due to high muscle deficiency and actin accumulation within myofibrils." (PMID 38001634, 2023). "Gene expression patterns in skeletal muscles from 7-day-old wild type and cofilin-2 deficient mice were analyzed to identify potential mechanisms by which cofilin-2 deficiency results in myopathy." (PMID 25874796, 2015). "The current work investigated the effects of the myopathy-causing p.R91C variant in Tpm3.12, a tropomyosin isoform expressed in slow-twitch muscle fibers, on the regulation of actin severing and depolymerization by cofilin-2." (PMID 38003645, 2023). "In this work, we analyzed how the p.R91C variant of Tpm3.12 found in myopathy patients affects the in vitro activity of cofilin-2, the muscle-specific isoform of the ADF/cofilin family of proteins that maintain their length through severing and depolymerization of actin filaments." (PMID 38003645, 2023). "Deficiency of cofilin-2 is associated with myopathy and may result in a reduced polymerization of actin filament, causing their accumulation in nemaline bodies, minicores and concentric laminated bodies." (PMID 31906061, 2019). "The deficiency of myosin-binding protein C and cofilin-2 in the present study may indicate the development of myopathy following the high lovastatin supplementation (6 mg/kg)." (PMID 31906061, 2019). "The mutation converts Ala-35 into Thr and significantly reduces the cofilin-2 protein level in skeletal muscle and impairs solubility when recombinant cofilin-2 is expressed in a bacterial system, suggesting that the myopathy-causing mutation is a loss-of-function mutation." (PMID 20737540, 2010). "Since knowledge of the effects of Tpm3.12 variants on the filament dynamics is limited, the goal of this work was to verify the hypothesis that through affecting cofilin-2 activity, Tn and myopathy-causing Tpm3.12 variants influence length maintenance and stability." (PMID 38003645, 2023). "Although it is well established that Tpm regulates cofilin-2, it is not known whether myopathy-causing mutations affect its activity." (PMID 38003645, 2023). "The cell cycle dysregulation may be related to the role of cofilin-2 in regulating mitotic spindle formation, although it is also seen in certain myopathies and dystrophies not linked to cofilin-2." (PMID 25874796, 2015). "In line with this notion, lack of CFL2 regulation, as observed in CFL2-deficient mouse models or human mutations of CFL2, results in progressive sarcomeric disruption and actin accumulation due to reduced depolymerization of actin filaments that lead to myopathy." (PMID 33339131, 2020).
CFL2 also shares sentences with these, for which no sentence is quoted: myofibrillar myopathy (2 papers); centronuclear myopathy (1); chronic periodontitis (1); colorectal cancer (1); glial tumors (1); hepatocellular carcinoma (1); hereditary spastic paraplegia (1); Insulin resistance (1); lymph node metastases (1); melanoma (1); metastatic melanoma (1); myocardial infarction (1); nasopharyngeal carcinoma (1); nemaline myopathy type 7 (1); osteoarthritis (1); ovarian carcinoma (1).